KCNH2 (potassium voltage-gated channel subfamily H member 2)
Diseases named in the same sentence as KCNH2 in open-access papers (continued):
Sharing a sentence is not in itself a finding about the gene and the disease.
adrenal hyperplasia (1 paper, 2019). "The promoter methylation of KCNH2 and CYP21A2 genes, which are known as a regulator of apoptosis and associated adrenal hyperplasia, was measured by BSC in the three pairs of CMTs and adjacent normal samples." (PMID 31569550, 2019).
anaplastic thyroid cancer (1 paper, 2023). "Furthermore, the KCNH2 gene influenced UCEC cell proliferation and regulated the migration of human anaplastic thyroid cancer cells, a result consistent with our finding that THCA patients with high hERG expression had a poor prognosis." (PMID 36792990, 2023).
Andersen-Tawil syndrome (1 paper, 2022). "Genetic screening revealed heterozygous variant c.635G>A (p.Arg218Gln) in the KCNJ2 gene, a known cause of Andersen-Tawil syndrome, and additional rare variant p.Thr983Ile in the KCNH2 gene." (PMID 35456365, 2022).
autoimmune disease (1 paper, 2023). A disorder resulting from loss of function or tissue destruction of an organ or multiple organs, arising from humoral or cellular immune responses of the individual to their own tissue constituents. "Interestingly, one of the subsets highly expressing the hERG1 encoding gene KCNH2 is the Treg compartment, further stressing the possibility that this channel would exert a role in the onset of autoimmune diseases, hence representing a novel biomarker." (PMID 37744334, 2023).
brain cancer (1 paper, 2024). A primary or metastatic malignant neoplasm affecting the brain. "Microarray data from publicly available gene expression database Oncomine was extracted to examine the expression level of KCNH2 in different histological subtypes of human brain cancers, relative to normal brain tissue." (PMID 39240809, 2024). "Analysis of KCNH2 mRNA levels in human brain cancer tissues." (PMID 39240809, 2024). "Bioinformatics data, obtained from Oncomine, indicates that KCNH2 gene is expressed differentially independent of brain cancer histological subtypes." (PMID 39240809, 2024).
cervical squamous cell carcinoma (1 paper, 2023). A squamous cell carcinoma arising from the cervical epithelium. "KCNH2 was significantly differentially expressed in samples grouped by CNV type in 10 tumours (GBMLGG, LGG, cervical squamous cell carcinoma and endocervical adenocarcinoma (CESC), BRCA, STES, SARC, KIRP, mesothelioma (MESO), PAAD, OV)." (PMID 36792990, 2023).
cocaine dependence (1 paper, 2022). A psychologically and socially impaired state, with or without physiological changes, that develops as a result of using cocaine and which leads to compulsive behaviors to acquire the substance. "KCNH2, a Potassium Voltage-Gated Channel Subfamily H Member 2, component of potassium channels, was also detected in our study associated with pergolide mesylate, a drug used to treat cocaine dependence." (PMID 36745154, 2022).
colon adenocarcinoma (1 paper, 2023). "In addition, there was a significant correlation between KCNH2 expression and m6A level in various tumours, such as colon adenocarcinoma (COAD), uveal melanoma (UVM), and LGG." (PMID 36792990, 2023).
dyspepsia (1 paper, 2023). An uncomfortable, often painful feeling in the stomach, resulting from impaired digestion. "Fourteen genes corresponding to two gene sets were identified, and the functional dyspepsia-related genes targeted by the activated F. fructus compound were ADRA2A, BDNF, CCK, CRP, GCG, JUN, Kcnh2, PTGS1, PTGS2, Pyy, SLC6A4, and TRPV." (PMID 37375548, 2023).
endometriosis (1 paper, 2025). The growth of functional endometrial tissue in anatomic sites outside the uterine body. "SSTR5, KCNH2, CASP3, PTGER1, PPARD, and TYMP emerged as the top-ranked targets, indicating their potential significance in the treatment of endometriosis." (PMID 39754173, 2025).
invasive breast carcinoma (1 paper, 2018). A carcinoma that infiltrates the breast parenchyma. "In the Gluck’s and Finak’s studies, KCNH2 was significantly upregulated in invasive breast carcinoma and it was ranked among the top 2% and 23% overexpressed genes respectively." (PMID 29423049, 2018).
Kleefstra syndrome 2 (1 paper, 2023). "A 7q36.1q36.2 deletion containing several pathogenic genes, including DPP6, KMT2C, ASB10, PRKAG2, KCNH2, among which KMT2C is a causative gene for Kleefstra syndrome 2 (MIM#617768)." (PMID 37892645, 2023).
lung squamous cell carcinoma (1 paper, 2023). "Furthermore, we assessed the impact of sex, and seven tumours [BRCA, SARC, KIRP, kidney renal clear cell carcinoma (KIRC), lung squamous cell carcinoma (LUSC), LIHC, and BLCA] were detected to have differential expression of KCNH2 between males and females." (PMID 36792990, 2023).
metastatic melanoma (1 paper, 2021). A melanoma that has spread from its primary site to another anatomic site. "CYT-high metastatic melanomas had recurrent copy number amplifications in loci 1p12 (NOTCH2), 1q44 (OR2M4), 7q36.1 (KCNH2), 11q13.3 (FGF3/4), 12p11.23 (MED21) and 12q13.3 (R3HDM2) and deletions in 1p22.1 (RHOC, NRAS), 9p21.3 (CDKN2B), 10q23.2 (miR346), 11q23.3 (ATM, CHEK1, ETS1) and 15q15.3 (CASC4)." (PMID 33779796, 2021).
oral cancer (1 paper, 2023). "Suggestive evidence from both analyses suggests that KCNH2 inhibition may lower the risk of oral cancer." (PMID 38089045, 2023). "Similarly, SMR analysis demonstrated that a higher expression of KCNH2 (target of beta-adrenoceptor blockers) was linked to a greater risk of oral cancer (OR = 2.223, 95% CI = 1.094–4.516)." (PMID 38089045, 2023). "IVW-MR analysis also provided suggestive evidence of an association between KCNH2-mediated DBP and risk of oral cancer (OR = 1.197, 95% CI = 1.028–1.394, p = 0.020), suggesting that KCNH2 inhibition may be a protective factor against oral cancer." (PMID 38089045, 2023).
rectum adenocarcinoma (1 paper, 2023). An adenocarcinoma arising from the rectum. "NAL, a new metric for assessing the immunotherapy response, showed a negative correlation with high KCNH2 expression in COAD, COAD/rectum adenocarcinoma oesophageal carcinoma (COADREAD), and UCEC." (PMID 36792990, 2023).
sarcoma (1 paper, 2023). A usually aggressive malignant neoplasm of the soft tissue or bone. "m6A is removed by demethylases such as FTO and ALKBH5, whose expression levels were significantly correlated with those of KCNH2 in PRAD, sarcoma (SARC), PAAD, and TGCT." (PMID 36792990, 2023).
Strabismus (1 paper, 2021). A misalignment of the eyes so that the visual axes deviate from bifoveal fixation. "Despite the small sample study, we were able to identify four genes (FAT3, KCNH2, CELSR1, TTYH1) with causative associations with strabismus." (PMID 33435129, 2021). "As a result, we found risk variants in four genes (FAT3, KCNH2, CELSR1, and TTYH1) in five families, suggesting their role in development of familial strabismus." (PMID 33435129, 2021).
cancer (96 papers, 2005 to 2025). A tumor composed of atypical neoplastic, often pleomorphic cells that invade other tissues. "Here, we explored the differential expression, diagnostic and prognostic value, RNA modifications, mutations, and immune implications of KCNH2 across cancers." (PMID 36792990, 2023). "We found that KCNH2 was significantly differentially expressed in all 32 tumours and had good diagnostic value in 10 cancers." (PMID 36792990, 2023). "We further investigated the prognostic impact of KCNH2 in cancer patients by Cox risk regression proportional models." (PMID 36792990, 2023). "KCNH2 is differentially expressed in over 30 cancers and has a high diagnostic value for 10 tumours." (PMID 36792990, 2023). "Concerning genetic risk after the onset of adolescence, women with pathogenic variants in KCNQ1 (LQTS1) and KCNH2 (LQTS2) are at increased risk of malignant arrhythmias, especially LQT2 due to a pore loop pathogenic variant." (PMID 37082456, 2023). "More recently, high-throughput exome sequencing revealed that out of 2480 Japanese cancer patients, 36 patients had KCNH2 mutations." (PMID 36792990, 2023). "The potassium channel ERG1, encoded by KCNH2, is expressed in a series of cells including neurons, smooth muscular cells, and cardiac cells, even cancer cells." (PMID 36066699, 2022). "Another example is a cancer patient with cardiovascular KCNH2 genetic variants; EKG showed the QTc prolonged during the chemotherapy." (PMID 36009026, 2022). "The two members of the KCNH family of voltage-gated potassium ion (K+) channels, human ether-à-go-go type 1 (Eag1 encoded by KCNH1) and human ether-à-go-go-related gene (hERG encoded by KCNH2), have been implicated in cancer development and hold promise as therapeutic targets." (PMID 40126672, 2025). "We also evaluated the potential correlation of KCNH2 expression with 60 immune checkpoints and showed that KCNH2 was positively correlated with most immune checkpoints across cancers, especially THCA, UVM, and PRAD." (PMID 36792990, 2023). "The human Ether-à-go-go-related gene Kv11.1 (KCNH2 or hERG1) is expressed in several normal tissues, including cardiac tissue and smooth muscle, and in cancer cells it is regulated by several microRNAs relevant to tumor progression." (PMID 37408210, 2023). "For better cancer care, we should carefully monitor the EKG during chemotherapy if the patient carries KCNH2 genetic variants." (PMID 36009026, 2022). "Accordingly, KCNH2 is highly conserved in tumors of different histogenesis, and integrin-β1-KCNH2 complexes play a central role in cancer formation and progression." (PMID 35942524, 2022). "Here, exome sequencing analysis showed that KCNH2 clustered into a single network related to cancer development." (PMID 33178018, 2020). "Among ion channels, those encoded by the ether-à-go-go related gene 1 (hERG1 also named KCNH2) are often overexpressed in neoplastic cell lines and human primary cancers of different histogenesis." (PMID 26339650, 2015). "Overall, we found that KCNH2 and its interaction molecular are expected to be immune-related biomarkers for cancer diagnosis and prognosis evaluation, and are potential regulatory targets of singalling pathways for tumour development due to their significant role in cancers." (PMID 36792990, 2023). "This evidence further reinforces the importance of posttranscriptional RNA modifications in cancer progression, but it remains unclear whether there is an impact on tumours through the methylation of KCNH2." (PMID 36792990, 2023). "While KCNH2 expression is generally thought to be restricted to the adult brain and heart, there is growing evidence that it is expressed in smooth muscle tissue as well as in cancer cells of various histologies." (PMID 36792990, 2023). "Human ether-a-go-go-related gene K+ channels (hERG; Kv11.1, KCNH2) are expressed in multiple cancer cells including GB and control cell proliferation and death." (PMID 24516604, 2014).
cancer (continued). "Meanwhile, it has been shown that KCNH1 and KCNH2 accelerate the proliferation of non-excitable cell-derived cancer cells, which has nothing to do with their ion conduction function." (PMID 38905316, 2024). "On the other hand, CYP21A2 and KCNH2, for which the expressions were not clearly investigated in human cancer, showed a heavily methylated promoter in cancer compared with a rarely methylated one in normal cells." (PMID 31569550, 2019). "KCNH2 and CYP21A2 promoter regions consisting of 10 (chr16: 15,042,868–15,043,044) to 12 CpG sites (chr12: 1,451,023–1,451,292) were drastically hypermethylated in cancer samples when compared with normal." (PMID 31569550, 2019). "These were chosen based on their gene expression patterns in cancer according to the literature survey: KRT5 and MMP7 for increased gene expression in cancer, KCNH2 for ambiguous expression in cancer, and CYP21A2 for unknown expression in BC." (PMID 31569550, 2019). "However, a comprehensive analysis of KCNH2 across cancers is currently lacking." (PMID 36792990, 2023).
tumor (73 papers, 2000 to 2026). "One study of the DNA methylation profile of clear cell OC tumors found hypermethylation and reduced mRNA expression of KCNH2; the low levels of KCNH2 in clear cell OC was associated with good prognosis, emphasizing the tumor-promoting role of these channels." (PMID 37375748, 2023). "KCNH2 expression is correlated with tumour mutation burden, microsatellite instability, neoantigen load, and mutant-allele tumour heterogeneity." (PMID 36792990, 2023). "Mutations and RNA methylation modifications (especially m6A) of KCNH2 are associated with its expression in multiple tumours." (PMID 36792990, 2023). "We used the SNV data for KCNH2 and its structure to map the mutational landscape of tumours, and we found that a large number of missense mutations were concentrated in the transmembrane segments of the full-length structure of KCNH2." (PMID 36792990, 2023). "In the analysis of MATH, representing malignancy, high KCNH2 expression was associated with increased MATH in 11 tumours." (PMID 36792990, 2023). "In OC tumor tissues, higher KCNH2 mRNA and protein expression were found when compared with adjacent non-tumor tissues, and the higher expression of KCNH2 has been associated with lymph node metastasis (LNM) and distant metastasis." (PMID 37375748, 2023). "The tumours most significantly associated with KCNH2 expression were SARC, KIPAN, THCA, and PRAD, and we further analysed the level of immune cell infiltration by the "Timer" method and the "EPIC" method." (PMID 36792990, 2023). "In addition, KCNH2 expression is associated with the tumour immune microenvironment and its immunosuppressive phenotype." (PMID 36792990, 2023). "Moreover, the KCNH2 channel has been identified to be associated with the Wnt/β-catenin pathway in focal adhesion by interacting with β1-integrin to influence tumour invasiveness." (PMID 36792990, 2023). "By analysing the relationship between KCNH2 expression levels and the levels of 3 types of RNA methylation modifications, we found that KCNH2 was associated with almost the expression levels of almost all assessed writers, erasers, and readers in the 4 tumour types NB, GBM, PCPG, and OV." (PMID 36792990, 2023). "KCNH2 gene mutation may be related to the occurrence of tumours." (PMID 36792990, 2023). "In conclusion, this result not only provides new potential targets for intervention but also advances the understanding of the relevance of KCNH2 to tumours." (PMID 36792990, 2023). "We observed a correlation between KCNH2 expression and immune cell infiltration, especially in B cells, in most of the tumour types." (PMID 36792990, 2023). "We used clinical information from the samples to further characterize the differences in KCNH2 expression across tumour patient stages." (PMID 36792990, 2023). "Expression of KCNH2 is further variable by tumour histological subtype and may be examined through microarray data from gene expression database Oncomine." (PMID 39240809, 2024). "Further clarification of the relationship between tumours, oestrogen, and hERG expression may provide new insights into the roles of KCNH2." (PMID 36792990, 2023). "Here, we found that KCNH2 expression is generally higher in female tumour patients." (PMID 36792990, 2023). "Among those are ether-à-go-go-related (hERG1, Kv11.1, KCNH2) voltage-gated, fast inactivating human K+ channels that have been reported in several tumor entities including chronic myeloid leukemia (CML) cells." (PMID 32390841, 2020). "CAV1/3 and KCNH2 were enriched in this term; the CAV1 gene is thought to function as a tumor suppressor or modifier gene in mammary epithelia." (PMID 31569550, 2019). "In addition, several pathways closely related to tumour development, such as the FAK-related focal adhesion and MAPK pathways, were enriched un genes related to KCNH2." (PMID 36792990, 2023).
tumor (continued). "The promoters of DSP, FZD8, KCNH2, and PPP1R14A were methylated in 28%, 67%, 22%, and 78% of the 36 tumor samples, respectively, but not in control samples." (PMID 24260260, 2013).
heart disease (13 papers, 2011 to 2025). "Although the primary mechanism of QTc prolongation/TdP is known to be hERG blockade, many risk factors can contribute, such as KCNH2 gene mutation, electrolyte disturbances, pre‐existing heart disease, bradycardia, or gender." (PMID 36748725, 2023). "Here, we generated a panel of isogenic control and cardiac disease lines and investigated the disease phenotype in parallel in both hiPSCs and hESCs harbouring the same N996I KCNH2 mutation." (PMID 24213244, 2013).
cardiovascular disease (9 papers, 2017 to 2024). "Furthermore, no critical nucleotide substitutions for cardiovascular diseases, such as KCNQ1, KCNH2 and SCN5A, were found in the comprehensive NGS analysis." (PMID 35486589, 2022).
genetic disorder (1 paper, 2026). "Long QT syndrome Type 2 (LQT2) is a genetic disorder caused by missense mutations in the KCNH2 gene that encodes the potassium channel KV11.1." (PMID 41993318, 2026).
KCNH2 also shares sentences with these, for which no sentence is quoted: cardiac arrhythmias (86 papers); leukemia (12); long QT syndrome 2 (10); gastric cancer (8); dilated cardiomyopathy (7); hypertrophic cardiomyopathy (7); ovarian carcinoma (7); pancreatic cancer (7); myocardial infarction (6); polymorphic ventricular tachycardia (6); acute myeloid leukemia (5); Hypertension (5); adenocarcinoma (4); arrhythmogenic right ventricular cardiomyopathy (4); Barrett esophagus (4); dysplasia (4); hepatocellular carcinoma (4); Hyperinsulinemia (4); pancreatic ductal adenocarcinoma (4); asthma (3); Bradycardia (3); breast tumor (3); cardiac hypertrophy (3); colon cancer (3); cystic fibrosis (3); death (3); familial hypercholesterolemia (3); Hyperglycemia (3); ischemic heart disease (3); lung carcinoma (3).
A further 159 diseases each share a sentence with KCNH2 in 3 papers or fewer.